GPX2 (glutathione peroxidase 2)
Diseases named in the same sentence as GPX2 in open-access papers (continued):
Sharing a sentence is not in itself a finding about the gene and the disease.
Hepatic steatosis (1 paper, 2022). Steatosis is a term used to denote lipid accumulation within hepatocytes. "In a study on hepatocyte-specific NFE2L2-upregulation mice with diet-inducing hepatic steatosis, thioredoxin-1, glutathione peroxidase-2, and Nqo1 were increased, and oxidative stress markers decreased." (PMID 35405942, 2022).
ileal tumor (1 paper, 2013). "Subsequently, double knockout of Gpx-1 and Gpx-2 leads to bacterial-induced intestinal inflammation and, ultimately, ileal tumor formation and Gpx-2 decreases inflammation and tumors in response to inflammatory carcinogenesis." (PMID 23861820, 2013).
multinodular goiter (1 paper, 2025). Nodular goiter characterized by more than one discrete tissue mass. "In the patient with multinodular goiter who did not harbor a KEAP1 mutation, TG expression in the nodule was equivalent to that in the nonnodular parenchyma, while NQO1 and GPX2 expression was very low in both regions." (PMID 39373520, 2025).
pancreatic adenocarcinoma (1 paper, 2024). "We explored the expression of several antioxidants (NRF2, GPX2, SOD1,2) and NRF2 target genes (NQO1, HMOX1, TXN) in 179 tumors and 171 normal tissues from the TCGA/GTEx pancreatic adenocarcinoma (PAAD) dataset." (PMID 38782891, 2024).
periodontitis (1 paper, 2025). An acute or chronic inflammatory process that affects the tissues that surround and support the teeth. "The corresponding results revealed that, compared to control samples, IGKV2D-30 and CD34 were downregulated in patients with periodontitis, while GPX2, GSTA4, and NYNRIN were upregulated in patients with periodontitis." (PMID 41333919, 2025). "These genes have been previously implicated in oxidative stress (GPX2 and GSTA4), immune regulation (CD34 and IGKV2D-30), and RNA processing (NYNRIN), which are all biologically relevant to the inflammatory and immune mechanisms underlying periodontitis." (PMID 41333919, 2025). "On the other hand, we found that peroxidase (GPX2) and glutathione S-transferase (GSTA4) are upregulated in the gingival tissue of periodontitis patients." (PMID 41333919, 2025). "The biological functions and mechanistic roles of the predicted genes—such as GPX2, CD34, and GSTA4—in the pathogenesis of periodontitis remain to be empirically confirmed." (PMID 41333919, 2025).
primary immunodeficiency (1 paper, 2025). "Notably, GPX2 was markedly enriched for pathways such as primary immunodeficiency, suggesting its relevance to inflammation." (PMID 41409301, 2025).
renal fibrosis (1 paper, 2021). A final common manifestation of a wide variety of chronic kidney diseases characterized by glomerulosclerosis and tubulointerstitial fibrosis. "An antioxidative transcription factor, NF-E2-related factor 2 (NRF2), is known to activate the transcription of glutathione peroxidase 2 (GPX2) to increase oxidative stress, inflammation, and apoptosis, leading to permanent injury with renal fibrosis and DKD." (PMID 34769288, 2021).
steatosis (1 paper, 2021). Increased lipid within the cytoplasm of cells. "Of these genes, 11 coded for selenoproteins of which four genes had lower expression (SELENON, SELENOO, GPX1, and TXNRD3) and seven genes had higher expression (SELENOK, SELENOS, SELENOW, GPX2, GXP3, DIO1, and SEPHS2) in steatosis." (PMID 34869521, 2021). "Two selenoprotein genes (GPX2 and GPX3) encompassed in the “glutathione metabolism” pathway had higher expression, and one gene had lower expression (OPLAH) in steatosis, suggesting an increase in glutathione utilisation." (PMID 34869521, 2021). "Amongst the 13 genes, eight (DIO1, GPX2, SEPHS2, SELENOK, SELENOS, SELENOT, SELENOF, and SELENOW) had higher, and five (DIO3, GPX1, SELENON, SELENOO, and TXNRD3) had lower expression in steatosis." (PMID 34869521, 2021). "Besides the selenoproteins GPX2, DIO1, and SEPHS2, the gene for TRNAU1AP also had higher expression in steatosis in the “selenium metabolism and selenoproteins” pathway, and TXNRD3 had lower expression in steatosis." (PMID 34869521, 2021).
thyroid nodule (1 paper, 2025). A small circumscribed mass in the THYROID GLAND that can be of neoplastic growth or non-neoplastic abnormality. "Immunohistochemical analysis of TG, NQO1, and GPX2 was performed using thyroid tissues of the same patient with the L136P mutation, and FC values in the thyroid nodule were 1.04, 55.47, and 496.64, respectively." (PMID 39373520, 2025).
thyroid tumor (1 paper, 2025). A benign or malignant neoplasm affecting the thyroid gland. "While Ogg1 mRNA expression was not modified, we observed a downregulation of Gpx2 and Nqo1 mRNA expression in thyroid tumors from 2- and 8-month-old RET/PTC3 Dicer1(+/+) mice compared to WT thyroids, suggesting that redox homeostasis is unbalanced in RET/PTC3 tumors." (PMID 41002430, 2025).
cancer (80 papers, 2007 to 2026). A tumor composed of atypical neoplastic, often pleomorphic cells that invade other tissues. "Meanwhile, the Hedgehog signaling pathway activator 20(S)-OHC reversed the downregulation of Hedgehog signaling and cancer stemness markers caused by GPX2 knockdown." (PMID 40533443, 2025). "High levels of GPX2 expression have been associated with increased malignancy, invasiveness, and poorer prognosis in various cancers, such as colorectal, pancreatic, lung, and cervical cancers." (PMID 41145471, 2025). "In animal models, the loss of both GPx1 and GPx2 results in ileocolitis and spontaneous cancer, underscoring the importance of these enzymes in cancer prevention." (PMID 39942544, 2025). "The oncogenic effects of GPX2 have been demonstrated in a variety of cancers and are associated with tumor progression." (PMID 38914724, 2024). "It was noticed that Gpx-2 was present in not only cancer cells but also stromal cells, particularly in cancer-associated fibroblasts (CAFs)." (PMID 37834097, 2023). "The high expression of Gpx-2 is associated with the growth metastasis and drug resistance of cancer cells, as well as a low patient survival rate." (PMID 37834097, 2023). "High expression of CPS1, FGG, and GPX2 has been frequently associated with poor prognosis of various cancers." (PMID 33493519, 2021). "GPX2 downregulation was associated with increased apoptosis in intestinal crypts, while upregulation was found to lead to malignant progression, cisplatin resistance, and worse outcomes in various cancers." (PMID 40649855, 2025). "Cancer development may be linked to alterations in GPX2 and GPX3 activities, which were associated with glutathione (C00051), oxidized glutathione (C00127), and hydrogen peroxide (C00027)." (PMID 37955007, 2023). "In addition, the level of several selenoproteins, including TXNRD1 and GPX2, have been linked to different cancers." (PMID 35163318, 2022). "In contrast, GPx2 OE in several carcinoma types was associated with poor prognosis." (PMID 35193955, 2022). "The mutation of normal cells into cancer cells might reverse the basic physiological functions associated with the GPX2 gene." (PMID 33706760, 2021). "We had previously shown that GPX2 is overexpressed in breast, liver, and castration-resistant prostate cancers, and clarified the molecular mechanisms underlying its regulation in cancer proliferation, in addition to its significance as a therapeutic target in these malignant tumors." (PMID 29662611, 2018). "By increasing antioxidant defenses, GPx2 helps cancer cells survive oxidative stress, contributing to tumor progression." (PMID 39942544, 2025). "Immunostaining for phosphorylated-AMPK (pAMPK) and GLUT1 (downstream of HIF1α), showed that GPx2 KD tumours were enriched in cancer cells expressing both metabolic markers." (PMID 38238426, 2024). "A common trope in studies on GPX2 roles across many cancer types is overexpression in low-expressing cell lines and reciprocal knockdown in high-expressing cell lines." (PMID 39329876, 2024). "These considerations add more levels of uncertainty in evaluating the possible role of GPX2 in cancer and general antioxidant function, particularly using cell lines, which by and large fail to replicate the high GPX2 and NOX1 levels of COAD/READ." (PMID 39329876, 2024). "It is conceivable that high GPX2 expression reflects tumor malignancy, and it is a significant factor in poor prognosis for cancer patients." (PMID 39125992, 2024). "Quantification of GPx2 KD tumours and paired lung mets confirmed a higher percentage of carcinoma cells co-expressing p63 with KRT8/KRT14 than with KRT8 or KRT4 at both sites." (PMID 38238426, 2024). "Immunostaining revealed that GPx2 KD tumours contained carcinoma areas that were KRT14, N-CAD, VIM positive and E-CAD negative as compared to control tumours, indicative of binary EMT." (PMID 38238426, 2024).
cancer (continued). "The link between GPx2-mediated Wnt activation and metastasis and cancer development is supported by recent studies." (PMID 37373256, 2023). "GPX2 overexpression has been characterized in several cancers such as colorectal adenomas and carcinomas, as well as promoting progression of lung adenocarcinomas." (PMID 37244126, 2023). "In this place, it should be pointed out that the role of Gpx-2 in cancer development varies at different stages of the disease." (PMID 37834097, 2023). "We also examined the intracellular distribution of Gpx-2 in cancer tissues using immunogold labelling." (PMID 37834097, 2023). "GPX2 regulates cancer progression by regulating the hydrogen peroxide level in the cells, so when the level of H2O2 is downregulated to a normal level and the oxidative stress is relieved, it can help in dysregulating cancer cell homeostasis." (PMID 35564184, 2022). "GPX-2 is an intriguing antioxidant particularly important for keeping cells safe in response to natural oxidizers (such as oxidative lipids) and for cancer cells, as protection against oxidative stressors, including chemotherapies." (PMID 35104504, 2022). "Thioredoxin reductase 1 (TR1), selenoprotein of 15 kDa (Sep15), and glutathione peroxidase 2 (GPx2) are the most studied members of this family in relation to cancer." (PMID 35267564, 2022). "Such a dual role of the GPX2 gene in cancer has recently been widely discussed, with it specifically being shown to reduce the levels of H2O2 and free radicals in normal cells and being reported as an anticancer enzyme." (PMID 33706760, 2021). "It was indicated that GPX2 was moderately elevated in cancers of brain and CNS, compared with that in normal tissues (P < 0.05)." (PMID 33552592, 2021). "The study first assessed the differences in mRNA expression of GPX2 in a series of human cancers and normal tissues using the Oncomine database." (PMID 33552592, 2021). "GPX2 mRNA expression was first assessed across various cancer types in oncomine and cancer cell lines from CCLE." (PMID 33552592, 2021). "It is quite different from the expression analysis that upregulation of GPX2 level is found in epithelium-derived carcinomas and involved in carcinogen-induced tumor initiation, tumor growth, and metastasis." (PMID 33552592, 2021). "Both Meta3 and Meta4 cells have high expression of many key markers of metaplasia, such as Wfdc2, Mal2, and Gpx2, and cancer stem cell (CSC) marker genes, such as Cd44, CD133 (Prom1), and CD166 (Alcam)." (PMID 31804471, 2019). "An integrated analysis focused on lipid metabolism and local immune response indicated HMGGCS2, CD36, and GPX2 as differential hub genes of lipid metabolism in the pan-cancer immune microenvironment." (PMID 31493764, 2019). "GPX2 catalyzes the reduction of organic hydroperoxides and hydrogen peroxide by glutathione in the intestine, protecting cells against oxidative damage, and together with other GPX2 provides a very important protection against inflammation and cancer." (PMID 29881384, 2018). "Yan and Chen reported that GPX2 expression is regulated by ΔNp63γ, and GPX2 overexpression can inhibit the apoptotic response of cancer cells to oxidative stress." (PMID 29662611, 2018). "Additional genes in this study, showing changes in gene expression for both the Irish and the Czech cancers were GPX2, GPX3, SELENOK, SEPHS2, SELENBP1, and SOD2." (PMID 30469315, 2018). "Although the up-regulation of GPX2 by the Wnt pathway had been reported, this is the first instance of a deregulation in cancer for ADH1B mRNA." (PMID 28962550, 2017). "In contrast, Cud C downregulated MYB1 (v-myb avian myeloblastosis viral oncogene homolog), CCNB1 (cyclin B1) and GPX2 (Glutathione peroxidase 2), which have been shown to promote cancer proliferation and metastasis." (PMID 28107519, 2017).
cancer (continued). "Three selenoproteins have been implicated in both prevention and promotion of cancer: the 15kDa selenoprotein (Sep15), thioredoxin reductase 1 (Txnrd1, TR1), and glutathione peroxidase 2 (GPx2)." (PMID 25886253, 2015). "Thus, GPx-2, the more sensitive GPx isomer to changes in dietary Se levels, is believed to play a larger role in shielding the gastrointestinal tract from oxidative stress, offering protection from oxidative processes-linked inflammation aliments and cancers of the gut." (PMID 24962481, 2014). "There are interactions between ITCs and Se in the up-regulation of thioredoxin reductase (TR-1) and glutathione peroxidase 2 (GPx2) and it is clear that ITCs and Se exhibit a plethora of multi-targeted effects in cancer chemoprevention." (PMID 25532034, 2014). "Based on these results, GPx2 obviously is able to enhance cancer development by suppressing apoptosis which otherwise eliminates damaged or transformed cells." (PMID 23977205, 2013). "This down-regulation of GPx2 in areas of advanced dedifferentiation fits with the postulated only transient up-regulation of GPx2 during cancer development." (PMID 23977205, 2013). "Taken together, the putative effect of GPx2, other selenoproteins, and probably selenium itself, essentially depends on the cancer stage and the involvement of inflammation." (PMID 23977205, 2013). "In conclusion, the role of GPx2 and presumably also of selenium depends on the cancer stage and obviously on the involvement of inflammation." (PMID 23977205, 2013). "The anti-inflammatory potential of GPx2 will help to inhibit cancer initiation and inflammation-triggered promotion, but its growth supporting potential will also support tumor growth." (PMID 22654914, 2012). "The benefit of upregulation/activation of the Nrf2 pathway of the selenoproteins TrxR1 and GPx2 differs in healthy and in cancer cells." (PMID 22654914, 2012). "Additional genes with known relevance to human cancer identified by this SNCP model included glutathione peroxidase 2 (GPX2), the mitotic checkpoint protein kinase BUB1B, and the progestin-induced protein DD5." (PMID 18425214, 2007). "GPX2, involved in oxidative stress regulation, may provide a survival advantage to cancer cells by counteracting elevated reactive oxygen species resulting from impaired DNA repair." (PMID 40870889, 2025). "Notably, inhibiting GPX2 enhances the efficacy of cisplatin by sensitizing cancer cells to apoptosis." (PMID 41145471, 2025). "GPX2 is specifically expressed in epithelial cells, mainly in the gastrointestinal tract, but the organ specificity will be lost when normal cells are transformed into cancer cells." (PMID 40533443, 2025). "To further explore whether GPX2 has effects on glutathione metabolism and cancer stemness in vivo, we performed analysis of reducing equivalents and immunohistochemical staining." (PMID 40533443, 2025). "GPX2 is noted for a tendency of large increases or decreases in expression levels during tumorigenesis that leads to investigators focusing on its role in cancer." (PMID 39329876, 2024). "Additionally, GPX2, an antioxidant enzyme, played a significant role in tumor progression across various cancers by promoting metastasis through phenotypic and metabolic reprogramming." (PMID 39505867, 2024). "However, the majority of GPX2 cell proliferation research being done now focuses on cancer and other issues, and the effects on porcine adipocytes and skeletal muscle cells have not been reported." (PMID 38722949, 2024). "GPx2 was identified as a target of the Wnt signaling pathway and plays an important role in normal physiological processes, embryonal development, and pathological processes such as cancer." (PMID 38483584, 2024). "In addition, the development of cancers also involves contrasting levels of GPx2 expression, which are correlated with the progression of cancer and poor prognosis." (PMID 39404411, 2024).